CRP (C-reactive protein)
Diseases named in the same sentence as CRP in open-access papers (continued):
Sharing a sentence is not in itself a finding about the gene and the disease.
endothelial dysfunction (continued). "CRP is shown to mediate endothelial dysfunction by inhibiting endothelium-dependent NO-mediated dilation in retinal arterioles by producing superoxide from NADPH oxidase." (PMID 26339132, 2015). "Vaudo and associates have provided more recent evidence for endothelial dysfunction in young to middle-aged patients with low disease activity (disease activity score), DAS ≤3.2, and noted a strong association to average CRP levels." (PMID 23762554, 2013). "Flow-mediated arterial dilatation (FMAD) was assessed as a surrogate of endothelial dysfunction, and C-reactive protein (hsCRP) was determined as a marker of inflammation." (PMID 24222887, 2013). "The mechanisms that cause acute cardiovascular events in smokers include increased hypercoagulability leading to thrombosis, endothelial dysfunction, and development of chronic inflammatory state by an increase in white cells and CRP values." (PMID 23738053, 2013). "The chronical presence of proinflammatory cytokines as IL-1a, IL-1b, IL-6 and TNFα, and CRP from the synovial tissue directly influences the systemic endothelial dysfunction." (PMID 23762554, 2013). "In HAECs, C-reactive protein, the expression of which is related to inflammation as well as endothelial dysfunction, dose dependently increased HA release." (PMID 24171112, 2013). "On the other hand, it seems precipitated to extrapolate the results from this study and conclude that subjects with increased CRP levels have more endothelial dysfunction." (PMID 23864919, 2013). "Elevated C-reactive protein levels in patients with ED have been found in patients with endothelial dysfunction." (PMID 22973171, 2012). "Elevated C-reactive protein (CRP) levels caused by cigarette smoking, can also promote endothelial dysfunction by lowering the production of nitric oxide (NO) and diminishing its bioactivity." (PMID 21317997, 2010). "The inhalation of fine PM has been linked to both pulmonary and systemic inflammation, including increases in the circulating acute-phase marker CRP and increases in indicators of endothelial dysfunction and injury in the circulation." (PMID 19479011, 2009). "Leptin, however, induces mitochondrial superoxide production and MCP1 (monocyte chemotactic protein 1) expression in endothelial cells, endothelial dysfunction and CRP (C-reactive protein) expression." (PMID 19689798, 2009). "Frequently used agents such as cisplatin, bleomycin and etoposide, can cause thickening of the carotid artery intima, Raynaud's phenomenon, and an increase in plasma C-reactive protein (CRP), VWF and PAI-1, all associated with endothelial dysfunction." (PMID 18506173, 2008). "Two studies explored potential mechanisms linking CVD with CV outcomes, identifying elevated systemic inflammatory markers, such as C-reactive protein (CRP) and IL-6, and signs of endothelial dysfunction, including reduced flow-mediated dilation and increased arterial stiffness in patients with CVD." (PMID 40912305, 2026). "Despite aligning with evidence of persistent immune dysregulation in PCC (e.g., unresolved viral antigen persistence or endothelial dysfunction), it is noteworthy that CRP levels in our study were far below thresholds typically associated with severe systemic inflammation." (PMID 40650463, 2025). "CRP may exacerbate oxidative stress and endothelial dysfunction, thereby altering atrial electrophysiological properties and facilitating triggered activity." (PMID 40454729, 2025). "Lastly, we did not explore other biomarkers associated with endothelial dysfunction or chronic inflammation (such as C-reactive protein)." (PMID 41421665, 2025). "These conditions are associated with persistent immune activation and the production of pro-inflammatory cytokines, such as interleukin-6 (IL-6), tumor necrosis factor-alpha (TNF-α), and C-reactive protein (CRP), which exacerbate endothelial dysfunction and promote atherosclerotic plaque formation." (PMID 40001504, 2025).
endothelial dysfunction (continued). "Thus, elevated CRP can actively promote the low-grade endothelial dysfunction and leukocyte-mediated capillary damage observed in DR." (PMID 41159344, 2025). "CRP itself can further perpetuate endothelial dysfunction and coagulation." (PMID 40722588, 2025). "In cardiovascular and inflammatory diseases, suPAR often exhibits smaller absolute differences than traditional biomarkers (e.g., CRP or troponins) but retains prognostic value due to its pathophysiological specificity for immune activation and endothelial dysfunction." (PMID 40649045, 2025). "Consistent with these hematologic abnormalities, hyperglycemic patients showed significantly higher levels of ESR, CRP, ferritin, and fibrinogen, suggesting a pronounced proinflammatory milieu driven by oxidative stress, endothelial dysfunction, and activation of the IL-6/TNF-α cytokine axis." (PMID 41156159, 2025). "Mechanisms such as endothelial dysfunction, myocardial inflammation, and autonomic dysregulation were consistently supported across studies via imaging (e.g., cardiac MRI) and biomarkers (e.g., troponin, C-reactive protein (CRP))." (PMID 40438846, 2025). "CRP values appeared to have a similar influence on endothelial dysfunction in both groups." (PMID 40143236, 2025). "Smoking promotes CAS via C-reactive protein-induced IL-6 expression, nicotine activation of α7-nicotinic acetylcholine receptors, adrenergic stimulation, catecholamine release, endothelial dysfunction, oxidative stress, platelet activation, and increased blood viscosity." (PMID 41464622, 2025). "Additionally, CRDs reduced inflammation and endothelial dysfunction markers (CRP, IL-6, and E-selectin)." (PMID 40935153, 2025). "Although inflammatory mediators such as IL-6, TNF-α, and CRP are elevated across all three conditions, endothelial dysfunction and systemic cytokine signaling represent central converging mechanisms, linking local periodontal inflammation and metabolic dysregulation to cardiovascular complications." (PMID 41007869, 2025). "Although this research mainly concentrated on lipid peroxidation and lipid profiles, upcoming studies ought to incorporate biomarkers of inflammation and endothelial dysfunction, like CRP, IL-6, and adhesion molecules, to thoroughly assess the anti-atherosclerotic effects of GPHWE." (PMID 40298660, 2025). "In parallel, biochemical investigations reveal that bruxism intensity correlates positively with circulating inflammatory markers, including C-reactive protein (CRP) and fibrinogen, which are well-established mediators of endothelial dysfunction and atherogenesis." (PMID 41141201, 2025). "Evidence has also described higher concentrations of endothelial dysfunction markers decades postpartum, such as soluble vascular cell adhesion molecule-1, soluble E-selectin, sFlt-1, urinary albumin/creatinine ratio, and high-sensitivity C-reactive protein." (PMID 41375695, 2025). "The link between inflammation and endothelial dysfunction has been taken into consideration by other studies, which have shown that acute phase proteins such as inflammatory adhesion molecules and C-reactive protein (CRP) were simultaneously elevated during HP infection and endothelial dysfunction." (PMID 38398002, 2024). "Consequently, inflammation emerges as a key mediator of endothelial dysfunction, and CRP, a well-established marker of inflammation, has been shown to be closely associated with ED in numerous studies." (PMID 39634189, 2024). "CRP may contribute to endothelial dysfunction, inflammation, and vasoconstriction in the pulmonary arteries, thereby exacerbating the pathology of PAH." (PMID 39768778, 2024). "IL-6 stimulates CRP production, promotes endothelial dysfunction, and leads to plaque instability." (PMID 39057626, 2024). "Moreover, AF triggers the elevation of c-reactive protein and cytokines, exerting a proinflammatory effect on endothelial cells, potentially leading to endothelial dysfunction." (PMID 38994337, 2024).
endothelial dysfunction (continued). "The beneficial effects of statins may be facilitated by their ability to counteract CRP-induced endothelial dysfunction and oxidative stress." (PMID 39598120, 2024). "In the pediatric population, increased waist-to-hip ratio has been associated with elevated markers of inflammation, including CRP, IL-6, and MCP-1, as well as with markers of endothelial dysfunction, such as soluble intracellular cell adhesion molecule-1 (sICAM)." (PMID 38396489, 2024). "That may be explained by the direct involvement of CRP in the development of endothelial dysfunction, vascular stiffness, and by enhanced vascular response to angiotensin II and aldosterone." (PMID 37238705, 2023). "In recent years, several studies have shown that women with PCOS present with chronic low-grade inflammation, indicating abnormal expression of the proinflammatory cytokines interleukin-1 (IL-1), CRP, and interleukin-18 (IL-18), as well as endothelial dysfunction and increased oxidative stress." (PMID 37537636, 2023). "The proposed mechanism of decreased eNOS mRNA synthesis caused by CRP, resulting in endothelial dysfunction, is not the only one." (PMID 36293156, 2022). "Notably, inflammatory biomarkers such as C-reactive protein (CRP) and interleukins (IL) -1 and -6 have been widely explored as biomarkers of endothelial dysfunction and inflammation in clinical studies." (PMID 35663580, 2022). "Moreover, the MD reduces the circulation of inflammatory markers and endothelial dysfunction, such as C-reactive protein and E-selectin." (PMID 36014782, 2022). "Thus, the clinical-laboratory score for risk stratification of patients showed that DM, PaO2/FiO2 ratio, and the inflammatory and endothelial dysfunction markers CRP and LDH are predictive for IMV requirement." (PMID 35957939, 2022). "Potential biomarkers linking periodontitis with endothelial dysfunction, including C-reactive protein (CRP), interleukin (IL)-1, ICAM-1, E-selectin, vWF, plasminogen activator inhibitor type-1 (PAT-1), and plasminogen, have been found to be decreased after periodontal treatment." (PMID 36118034, 2022). "Moreover, CRP levels were correlated with endothelial dysfunction among DM populations, and CRP can predict DM complications." (PMID 35784528, 2022). "Inferring this to humans, CRP-induced effect may converge with other mechanisms, such as oxidative stress, to promote endothelial dysfunction and vascular diseases in AA." (PMID 34899053, 2021). "CRP may exert direct effects to aggravate endothelial dysfunction and induce augmented procoagulant responses." (PMID 34537026, 2021). "Patients with MetS may also exhibit micro-albuminuria, endothelial dysfunction and a pro-inflammatory and pro-thrombotic state, with increased circulating C-reactive protein (CRP), tumor necrosis factor-α (TNF-α) and interleukin-6 (IL-6)." (PMID 33777773, 2021). "The negative association between omentin, circulating IL-6 and C reactive protein was also shown to be related to endothelial dysfunction." (PMID 34261479, 2021). "C-reactive protein is a nonspecific biomarker of inflammation and a well-known causative factor of endothelial dysfunction." (PMID 34073616, 2021). "EDIH impacted inflammation and endothelial dysfunction biomarkers from +1.1% (TNF-αR2) to +7.8% (CRP) and reduced adiponectin by 2.4%; and for lipid biomarkers: +0.3% (total cholesterol) to +3% (triglycerides/total cholesterol ratio) while reducing high-density lipoprotein cholesterol by 2.4%." (PMID 34616762, 2021). "Elevated levels of plasma cystine (the disulphide form of cysteine) were positively associated with MI (vs. UA) and werepositively correlated with SYNTAX score II and hs-CRP, which is indicated to link with a higher oxidative stress and endothelial dysfunction." (PMID 33937325, 2021).
endothelial dysfunction (continued). "Therefore, galectin-3 together with CRP is associated with VRI values and is a potential endothelial function modulator and a valuable biomarker of endothelial dysfunction in patients with CKD." (PMID 34437403, 2021). "A growing body of evidence suggests that CRP could promote endothelial dysfunction by inducing the release of monocyte-chemoattractant protein-1." (PMID 32358950, 2020). "However, there is evidence that in addition to inhibition of HMG-CoA reductase to lower LDL-cholesterol, statins also reduce oxidative stress, endothelial dysfunction, and C-Reactive Protein." (PMID 32664962, 2020). "Recent analyses have shown that SLE-specific circulatory factors, TNF-α, interleukin-17, interferons, ligand of cluster of differentiation 40 (CD40L), and C-reactive protein (CRP), lead to endothelial dysfunction via promotion of abnormal eNOS function and enhanced oxidative stress." (PMID 32351667, 2020). "Increased CRP and reactive oxygen species (ROS) could trigger endothelial dysfunction that can increase the levels of ICAM-1 and VCAM-1, leading to increased monocyte chemoattraction, binding to LDL-molecules and increased risk for cardiovascular disease." (PMID 33269023, 2020). "C-reactive protein seems to be connected to endothelial dysfunction and foam cell formation." (PMID 33312065, 2020). "CRP was reported to be effective on endothelial dysfunction in a way that high levels may reduce nitric oxide production, increase endothelin 1, and up-regulate angiotensin type 1 receptor, therefore, influencing on renin-angiotensin-aldosterone system." (PMID 32489776, 2020). "The inflammation marker CRP may contribute to persistent obstruction of proximal PA by promoting vascular remodeling, endothelial dysfunction, and in situ thrombosis." (PMID 31948402, 2020). "Also, the urinary CRP significantly (p < 0.0001) positively correlated with the endothelial dysfunction marker ET-1, inflammatory markers IL-6 and AGP, and oxidative stress marker 8-OHdG." (PMID 31737180, 2019). "Increased concentrations of lactate dehydrogenase and C-reactive protein are particularly interesting, since the first is increased in endothelial dysfunction, vascular obstruction, and intravascular hemolysis, and the high levels of the second has been associated with vaso-occlusive events." (PMID 31366068, 2019). "C-reactive protein (CRP) is an acute phasereactant and indicator of inflammation that promotes lipid accumulation in theatherosclerotic plaque and exerts direct effects on endothelial cells, therebycontributing to endothelial dysfunction (Erbelet al., 2008)." (PMID 27727360, 2016). "Since it has been suggested that CRP levels could be considered to be an early endothelial dysfunction biomarker, we measured hsCRP, an inflammatory biomarker." (PMID 27612877, 2016). "CRP may detrimentally affect the vascular wall by reducing nitric oxide bioavailability and inducing endothelial dysfunction, which may impair insulin endocytosis in endothelial cells." (PMID 25105149, 2014). "Besides being a marker, CRP is an active mediator of endothelial dysfunction, arterial thrombosis, and atherogenesis." (PMID 24466039, 2014). "Furthermore, correlations between C-reactive protein (CRP), a marker of systemic inflammation, and markers of endothelial dysfunction have been reported in both type 1 and type 2 diabetic patients." (PMID 23717483, 2013). "Thus, given the importance of CRP-induced pro-oxidative effects and resultant eNOS inhibition, CRP appears to be a key molecule to accentuate endothelial dysfunction and contribute to blood flow dysregulation." (PMID 23966996, 2013). "CRP disturbs by itself the nitric oxide metabolism, situation that induces endothelial dysfunction." (PMID 24222887, 2013). "CRP enhances the expression of LOX-1 on endothelial cells, which may also be a mechanism by which CRP promotes endothelial dysfunction." (PMID 23950953, 2013).
endothelial dysfunction (continued). "One hypothesis is that higher hs-CRP levels could be accompanied by the reduced NO production and endothelial dysfunction." (PMID 22518282, 2012). "In that study, endothelial dysfunction correlated with average CRP levels and disease duration." (PMID 19606218, 2009). "In longstanding RA, endothelial dysfunction is predicted by the C-reactive protein (CRP) level." (PMID 19344530, 2009). "Inflammatory biomarkers (CRP, IL-6, fibrinogen), plasma viscosity, endothelial dysfunction markers (VWF, t-PA), and coagulation factors (VIII and IX, but not VII) were significantly higher in cases of MI/CHD death, but not in cases of incident angina compared with those who were CHD event free." (PMID 19682232, 2009). "Hyperlipidemia is an important pathogenic mechanism ofinflammatory endothelial dysfunction in patients with type 2 DM.In this study, lipids profile, MDA, CRP, ET-1, and CAMs levelswere elevated, and correlated in type 2 DM patients who performedor did not perform CABG." (PMID 17497038, 2007). "Additionally, prolonged endothelial dysfunction and subclinical inflammation, beyond measurable hs-CRP levels, within the infarct zone may sustain a localized prothrombotic state considerably after the acute phase." (PMID 41050872, 2025). "High levels of CRP can mediate the expression of adhesion molecules, reduce the production of NO, impair the antioxidant defense function of endothelial cells, and lead to endothelial dysfunction, which is considered an important factor in the occurrence of CI-AKI." (PMID 40182426, 2025). "Moreover, this scenario is further complicated by inflammatory responses to hypomagnesemia even if Mg2+ immunomodulatory function regulates NF-kB activation and cytokine production and limits systemic inflammation, such as C-reactive protein and endothelial dysfunction." (PMID 40732897, 2025). "Second, endothelial dysfunction might concurrently increase hs-CRP concentrations." (PMID 41402545, 2025). "Therefore, we hypothesized that CRP would increase the expression of endothelial dysfunction, inflammation, and oxidative stress biomarkers in SHR-expressing human CRP." (PMID 38627621, 2024). "Almost a decade ago, researchers demonstrated that raised-neutrophil lifespan is linked to plasma levels of C-reactive protein (CRP), alkaline phosphatase, and the New York Heart Association (NYHA) class, and could represent a novel measurement of tissue and endothelial dysfunction." (PMID 39202727, 2024). "Thus, we hypothesized that CRP affects the protein expression of biomarkers of endothelial dysfunction, inflammation, and oxidative stress in the aorta." (PMID 38627621, 2024). "Inflammation is traditionally measured with C-reactive protein (hsCRP), however there is interest in novel pro-inflammatory markers platelet-activating factor (PAF) and lipoprotein-associated phospholipase A2 (Lp-PLA2) that are specifically involved in endothelial dysfunction and inflammation." (PMID 37700354, 2023). "Among these markers, C-reactive protein (CRP), monocyte chemoattractant protein-1 (MCP-1), intercellular adhesion molecule-1 (ICAM-1), and vascular cell adhesion protein 1 (VCAM-1) have all been implicated in endothelial dysfunction and the development of vascular disease." (PMID 37570877, 2023). "In this regard, plasma CRP levels may represent a more appropriate integrated measure of basal IL-6 activity, another potential mechanism that may explain the relationship between inflammation and endothelial dysfunction." (PMID 36407366, 2022). "Cytokines showed synergic role when combined to a classic biomarker of systemic inflammation (CRP) and to an emerging marker of endothelial dysfunction (MR-proADM) and may have additive effect to better explain disease pathogenesis and suggest more targeted intervention." (PMID 35563218, 2022).